IL6 (interleukin 6)
Diseases named in the same sentence as IL6 in open-access papers (continued):
Sharing a sentence is not in itself a finding about the gene and the disease.
metabolic disorders (continued). "Serum interleukin-1, interleukin-6, tumor necrosis factor, haptoglobin, serum amyloid A and lactate were increased in cows with metabolic diseases from −8 and −4 weeks before calving, as well as during and after diagnosis of the disease." (PMID 30889779, 2019). "In the context of metabolic diseases, altered IL-6 mechanisms that decrease ICa,L density, reduce intracellular Ca transients and impair cardiac contractility are also likely to promote supraventricular arrhythmias." (PMID 30666212, 2018). "Oncostatin M (OSM), a member of the interleukin 6 (IL-6) family of cytokines, plays important roles in various biological functions, including inflammatory responses and metabolic diseases." (PMID 30134804, 2018). "Our observation that IL-6 correlates with various lipids (e.g., ceramide and palmitic acid), but not carbohydrates or amino acids, is consistent with the lipid signaling and IL6-mediated stress responses crosstalk in metabolic diseases." (PMID 29851973, 2018). "Interleukin-6 (IL-6) is a pleiotropic cytokine with hormone like activity that can influence vascular and metabolic diseases." (PMID 29194369, 2017). "Pro-inflammatory cytokines, including tumor necrosis factor α (TNFα), interleukin-6 (IL-6) and interleukin-1β (IL-1β), have shown to deteriorate normal cellular functions, leading to the metabolic diseases." (PMID 27338466, 2016). "Adipose tissue‐released IL‐6 might contribute to some metabolic diseases, along with chronic inflammation, inducing muscle dysfunction." (PMID 39764565, 2025). "Furthermore, significant inflammatory biomarkers, such as C-reactive protein (CRP), interleukin-6 (IL-6), and tumor necrosis factor-alpha (TNF-α), have been associated with both HT and metabolic disorders." (PMID 40362879, 2025). "On the other hand, patients with a high BMI have more adipose tissue and, consequently, secrete greater amounts of adiponectin, IL-6, and tumor necrosis factor, resulting in metabolic disorders and a decrease in skeletal muscle mass, making these patients more prone to frailty." (PMID 40779600, 2025). "Moreover, in obese individuals, visceral adipose expansion leads to the release of high levels of leptin, resistin, TNF-α, and IL-6, and low levels of adiponectin, which promote inflammation and metabolic disorders." (PMID 40095937, 2025). "Because IL‐6 is crucial to maintaining proper metabolism, this might explain why regular physical exercise ameliorates metabolic diseases by regulating IL‐6." (PMID 39764565, 2025). "Among these, C-reactive protein (CRP), interleukin-6 (IL-6), and tumor necrosis factor-alpha (TNF-α) are well-recognized markers of systemic inflammation and have been associated with reduced muscle and brain function, and metabolic diseases in older adults." (PMID 40699540, 2025). "The fact that some myokines may exert opposite effects in healthy conditions and in metabolic diseases (e.g., IL-6) is another difficulty in inferring the expected effects of changes in specific myokines on glucose homeostasis and muscle mass." (PMID 40171198, 2025). "In addition to the relationships with metabolic diseases, excessive fat accumulation can generate inflammatory responses by releasing IL-6 into the circulation, while it releases IL-10 as an anti-inflammatory strategy." (PMID 38792922, 2024). "Activation of the classical pathway of IL-6 may be important for improving metabolic disorders in patients with T2DM." (PMID 39749325, 2024). "Some metabolic diseases that are simultaneously associated with aging can be easily identified and managed by assessing specific biomarkers (e.g., pro-inflammatory cytokines—tumor necrosis factor-alpha (TNF-α) and interleukin-6 (IL-6))." (PMID 39123632, 2024). "Interestingly, despite the well-described pro-inflammatory effects of IL-6 in metabolic disease, it has been shown that IL-6 released from SM in response to exercise exerts different effects, mostly acting in a hormone-like fashion." (PMID 37108574, 2023).
metabolic disorders (continued). "The same effect was observed following a high-fat diet in knock-out mice, where IL-6 upregulation was associated with a sort of a protective role in the absence of Tff3 when it came to metabolic disorders." (PMID 37108475, 2023). "Second, the retrospective nature of the study limited our ability to measure other measures of metabolic disease, including waist circumference, and visceral adipose tissue, and measures of inflammation, such as C-reactive protein, procalcitonin, and interleukin-6 levels." (PMID 37602105, 2023). "Moreover, chronic inflammation (as assessed by different biomarkers such as proinflammatory adipokine, leptin, and/or proinflammatory cytokines IL-6 and IL-1β) has been described to play a crucial role in the development of metabolic disease." (PMID 36006128, 2022). "The reconstitution of FoxO1 using IL-6-deficient mice and pharmacological treatment did not protect against metabolic disorder but prevented SMC hyperproliferation." (PMID 35896539, 2022). "Blocking IL-6 trans-signaling prevents HFD-induced metabolic disorders in mice." (PMID 36276810, 2022). "Despite the well-described pro-inflammatory effects of systemic IL-6 in metabolic diseases, clinical studies demonstrate that IL-6 secreted by skeletal muscle in response to physical exercise exerts anti-inflammatory effects with beneficial metabolic responses." (PMID 35631195, 2022). "GrimAge residuals showed associations with a broad range of blood-based biomarkers implicated in age-related disease and premature mortality risk, including inflammation (CRP, WBC, IL-6, and TNF-α), oxidative stress (GGT), neuropathology (GFAP), and metabolic disease (MetS)." (PMID 36153327, 2022). "Furthermore, IL-6 has been described as a major contributor to the anti-inflammatory effects of exercise in both healthy individuals and patients affected by metabolic disorders undertaking regular PA." (PMID 33924887, 2021). "Besides the production of IL-6 in activated immune cells, the systemic elevation of IL-6 in patients with metabolic diseases has strengthened the link between IL-6 and inflammation." (PMID 30678702, 2019). "Therefore, screening for substances that are able to mimic exercise by inducing interleukin-6 (IL-6) expression is important for the treatment of metabolic diseases." (PMID 28469249, 2017). "Taken together, our findings suggest that MTMR14 deficiency evokes severe inflammation via the up-regulation of TNF-α and IL-6, and the metabolic disorders may depend on elevated leptin and decreased adiponectin." (PMID 26697164, 2015). "Furthermore, IL-6 is one of the major adipokines involved in adiposity-related inflammation and metabolic disease." (PMID 25797257, 2015). "Obese and overweight prepubertal children have elevated serum levels of IL-6, and haptoglobin and TGF-β1 which are known as markers of inflammation that may increase the cardiovascular and/or metabolic disease risk." (PMID 27275205, 2015). "Thus, while classical IL-6 signaling appears to be closely linked to metabolic diseases and MASLD, the association between IL-6 trans-signaling and MASLD or MASH remains unclear, and the underlying mechanisms remain unknown." (PMID 41362820, 2026). "While no universally accepted cutoff exists for IL-6, cohort studies have demonstrated that even modest elevations predict increased risk of cardiovascular and metabolic disease, suggesting that the reductions observed here may carry clinical significance." (PMID 41302175, 2025). "Therefore, increased IL-6 may contribute to the severity of the disease as a combination of both inflammation and metabolic disorders." (PMID 40005437, 2025). "GM dysbiosis and inflammation also induce epigenetic alterations in cytokine genes, such as IL-1β, IL-6, TNF-α, NF-kB, BTLA, IL-18R1, TGF-β, P13k/Akt1, Ctnnb1, and Hsp90aa1, as well as DNMTs, HDACs, and DAT1 associated with the development and progression of metabolic disorders and/or NPDs." (PMID 41228440, 2025).
metabolic disorders (continued). "Therefore, modulation of the IL-6 signaling pathway toward the classical model may be more effective in correcting metabolic disorders than simply blocking the trans-signaling pathway." (PMID 39749325, 2024). "Therefore, in children with OSA, an increase in BMI coupled with a rise in circulatory IL-6 levels could serve as an early indicator of the potential development of metabolic disorders." (PMID 39201638, 2024). "The inflammatory biomarkers CRP and IL-6 were also significantly greater in the Cd-exposed group than in the control group, with increasing CRP (p < 0.01) and increasing IL-6 (p < 0.0001), indicating that CdCl2 is important in causing inflammation and metabolic disorders." (PMID 39593801, 2024). "Hence, this endocrine disruptor may be responsible for the development of metabolic disorders, promoting in fat cells an increase in proinflammatory pathways and upregulating the expression and release of certain cytokines, such as IL6, IL1β, and TNFα." (PMID 37175934, 2023). "However, the effect of IL-6 on metabolic disorders has been debated for several decades." (PMID 34576181, 2021). "However, this did not exclude the occurrence of metabolic disorders (less than 3 criteria), which is the probable cause of similar IL-6 and irisin concentration levels in both groups." (PMID 32872598, 2020). "HD predominantly influences physiological health through its role in inflammatory response (CRP, IL-6, TNF-α), oxidative stress, and metabolic disorders." (PMID 40191209, 2025). "For example, a study demonstrated that remodeling of the ECM in adipose and muscle tissue plays a pivotal role in metabolic disease development, identifying genes such as TCF7L2, ADIPOQ, CD36, PPARG, IL6, SIRT1, and COL5A1 as key regulators of inflammation." (PMID 41303617, 2025). "The fish oil inhibited inflammatory cytokines, such as tumor necrosis factor (TNF-α) and interleukin-6 (IL-6) levels in patients with NAFLD and other metabolic disorders." (PMID 40416371, 2025). "IL-6 and TNF-α levels are significantly higher in patients with metabolic disorders, including women with PCOS, also due to chronic inflammation." (PMID 40647668, 2025). "VAT is active in releasing bio-active factors such as leptin, adiponectin, tumor necrosis factor-α, interleukin-6, interleukin-8, and MCP-1 that are involved in the pathogenesis of CVD, metabolic disorders, and T2DM." (PMID 37964956, 2023). "Therefore, the reduction in inflammation in diabetic mice treated with rutin might be due to the increase in Sutterella abundance, which was positively related to the decrease in serum IL-6, suggesting that the effect of rutin on the flora might be related to metabolic disorders." (PMID 36966186, 2023). "Many studies have shown that pro-inflammatory cytokines and chemokines such as TNF-α, IL-6, MCP-1, and IL-1β in the liver play key roles in the progression of metabolic diseases." (PMID 36676939, 2022). "Therefore, the reduction of inflammation by TBF treatment in diabetic mice might be due to the increased abundance of Sutterella, and it was also positively correlated with the decrease in serum IL-6, suggesting that TBF effects on microbiota might be associated with metabolic disorders." (PMID 36016679, 2022). "Results of the study of hormonal and metabolic disorder connections in ACC patients have revealed higher tumor necrosis factor alpha (TNF-α), interleukin 6 (IL6) and monocyte chemoattractant protein 1 (MCP1) levels." (PMID 33578890, 2021). "Humans with metabolic diseases have increased plasma concentrations of tumor necrosis factor-α (TNF-α), interleukin-6 (IL-6), IL-1β, C-reactive protein and other inflammatory mediators." (PMID 33776749, 2020). "Overweight adolescent girls with PCOS and metabolic disorders (MD+/OW) showed higher CRP, leptin, and a two-fold increase in IL-6 and IL-18 concentrations compared to the control group of healthy girls (p < 0.05 for all parameters)." (PMID 32397375, 2020).
metabolic disorders (continued). "The production of ceramide in the liver increased the secretion of cytokines such as IL-6, TNF-α, and IL-1β, which should contribute to enhancing inflammatory responses in metabolic diseases." (PMID 32547402, 2020). "The TNM stages were significantly positively correlated with metabolic disorders such as fasting glucose (r = 0.17, p < 0.05) and inflammation status (hs-CRP, r = 0.22; IL-6, r = 0.35, p < 0.05)." (PMID 32293339, 2020). "Proinflammatory cytokines such as IL-6 and TNF, can dramatically mediate metabolic disorders as well as enhance catabolism of OA joint tissue." (PMID 33036557, 2020). "Inflammatory markers were WBC, CRP, IL-6 and -8, TNF-alpha and fibrinogen, and comorbidities comprised a broad panel including cardiac and metabolic disorders." (PMID 32601330, 2020). "The literature will state however that IL-6 and TNF-α are often significantly higher in people with a range of metabolic disorders." (PMID 32443433, 2020). "Inflammatory cytokines, including MCP-1, IL-6, IL-8, and TNF-α, which are secreted by adipose tissue, make major contributions to adipose tissue dysfunction and metabolic disorders." (PMID 31871428, 2019). "During the development of metabolic disorder, adipose tissue is considered to be a major source of inflammatory mediators, such as TNF-α, IL-1β, IL-6 and IL-17, which negatively affect adipocyte function." (PMID 30709353, 2019). "STAT3 is a transcription factor that can be activated by IL-6, EGF, and other cytokines, and plays a key role in various biological processes, such as inflammation, cell proliferation, migration, survival, and metabolic disorders." (PMID 27474168, 2016). "In fact, a number of systematic reviews have shown the association between inflammatory biomarkers, such as CRP, IL-1β, IL-6, TNF-α, IL-4, or IL-10, and cardio-metabolic diseases." (PMID 27527152, 2016). "There is a clear association between the inflammatory biomarkers used to calculate the DII score (CRP, IL-1β, IL-6, TNF-α, IL-4, and IL-10) and cardio-metabolic diseases such as obesity, diabetes, or CVD." (PMID 27527152, 2016). "Clinical data show that high IL6 levels are positively correlated with visceral fat area (VFA) and serum triglyceride (TG) concentrations, it is suggested that IL6 plays a central role in BPA-induced metabolic disorders." (PMID 41226680, 2025). "Patients with metabolic disorders have significantly higher levels of TNF-α and IL-6." (PMID 40837641, 2025). "Second, integration of objective biomarkers of inflammation (e.g., CRP, IL-6, TNF-α) could help clarify mechanistic pathways linking metabolic disease and psychiatric comorbidity." (PMID 41149069, 2025). "Likewise, leptin, a hormone involved in appetite regulation and energy balance and associated with a variety of metabolic diseases, and other pro-inflammatory cytokines such as IL-6 and TNF-α are essential in the pathophysiology of metabolic diseases." (PMID 39822427, 2024). "Therefore, given its critical relevance in metabolic disorders, we conducted an unprecedented investigation into the serum levels of NOV among CAD patients, as well as its correlation with TNF-α, IL-6, and various biochemical parameters." (PMID 37919772, 2023). "In addition, other bioactive factors, such as leptin, adiponectin, tumor necrosis factor-α, interleukin-6, interleukin-8, and MCP-1, can also be released from perirenal fat, which is involved in the pathogenesis of CVD, metabolic disorders, and T2DM." (PMID 35370949, 2022). "As the most important component of bacterial endotoxin, LPS has been shown to aggravate metabolic disorders by elevating IL-1β, TNF-α, and IL-6 expression, which might be related to TLRs." (PMID 35774596, 2022). "Moreover, supplementation with 25(OH)D can improve metabolic disorders and alleviate inflammatory response of T2DM patients via reducing a number of inflammatory factors such as IL-6, CRP, and TNF-α levels." (PMID 36619542, 2022).
metabolic disorders (continued). "Research has indicated that Artemisia plant extracts could prevent metabolic disorders induced by a high-fat diet in mice by downregulating the expression of CD36, TNF-α, IL-6, IFN-α and IFN-β genes in epididymal adipose tissue." (PMID 35625074, 2022). "In our MHO population, the reduction of IL-6 levels after two different time periods (12 and 24 months) could be protecting this phenotype MHO from the development of metabolic disorders throughout life." (PMID 35053667, 2022). "Consistent with the previously reported role of inflammation in this relationship, age was positively correlated with 5 of the 14 immune measures that VSURF selected as important predictors of the metabolic disease score, including LBP, CRP, IL-6, ICAM-1, and SAA." (PMID 34006628, 2021). "In the present study, we observed that FO and PO had similar adjusting roles on body weight, glucose, insulin, TG, TC, IL-6, and adipocyte counts in C57BL/6J mice fed a HF diet, indicating comparable regulations in metabolic disorders and inflammation between marine and plant ω−3 PUFA." (PMID 34168108, 2021). "HW significantly suppressed PMA-induced lipid accumulation, ROS generation, and IL-6 secretion in OP9 cells, suggesting it might prevent the development of metabolic disorders." (PMID 33799840, 2021). "Interestingly, saturated fatty acids were found to induce the release of pro-inflammatory cytokines, such as IL-6, IL-1β and TNF-α, from immune cells into blood circulation, particularly in individuals with metabolic disorders." (PMID 34681074, 2021). "Given the disease-related changes in levels of relevant cytokines (for instance, leptin, adiponectin, reisitin, FGF21, Fetuin A, TNF-α, IL-6, MCP-1), these factors may serve as biomarkers for the early detection of metabolic disorders." (PMID 31736870, 2019). "Increased visceral fat is related with metabolic diseases and inflammation, in association with an increased concentration of pro-inflammatory leptin, TNF-α, and IL-6 by increased adipose tissue, rather than subcutaneous fat." (PMID 30558262, 2018). "The implication of altered IL-6/IL-6R signaling for arrhythmias in patients with metabolic disorders is currently not clear." (PMID 30666212, 2018). "In the present study, olmesartan exerted a suppressive effect on adipocyte hypertrophy concomitant with an inhibitory effect on the IL-6-oxidative stress axis without any body weight reducing effect in KKAy mice, a human model of metabolic disorders." (PMID 24991574, 2014). "However, normal interleukin-6 level and IgG index of cerebrospinal fluid and brain magnetic resonance imaging and single photon emission computed tomography findings suggested that her neurological symptoms were caused by metabolic disorder but not neuropsychiatric systemic lupus erythematosus." (PMID 23956915, 2013). "Taken together, our study demonstrated that PMQ up-regulates adiponectin expression via a mechanism that implicates PPARγ together with TNF-α and IL-6, suggesting that PMQ might be a potential candidate for the treatment of metabolic diseases." (PMID 21734632, 2011). "The effects of autophagy deficiency on endMT were independent of the TGFβ pathway but IL-6-dependent: IL-6 neutralizing antibody prevented endMT in ATG5 knock-down human microvascular cells and ameliorated metabolic disorders in endothelial-selective ATG5 deficient mice fed with high fat diet." (PMID 36980288, 2023). "In metabolic disorder like T2DM, the adipose-resident macrophages are polarized towards a pro-inflammatory (M1-polarized) phenotype, increasing the expression of inflammatory mediators, including interleukin-6 (IL-6), tumor necrosis factor-α (TNF-α), and IL-1β." (PMID 35173531, 2022).